PIWIL1 (piwi like RNA-mediated gene silencing 1)
Diseases named in the same sentence as PIWIL1 in open-access papers (continued):
Sharing a sentence is not in itself a finding about the gene and the disease.
tumor (67 papers, 2005 to 2026). "A previous study revealed a significant association of PIWIL1 and piR-823 in the tumor tissue of patients with RCC." (PMID 41596471, 2026). "Accordingly, Raeisossadati et. al. showed an association of PIWIL1 mRNA expression with tumor invasion depth and tumor stage." (PMID 38303021, 2024). "The ectopic expression of PIWIL1 has recently been implicated in tumor differentiation and depth of invasion, as well as lymph node invasion and metastasis." (PMID 35637965, 2022). "Our findings here showed that PIWIL1 drives FAO as a source of ATP generation in differentiated HCC cells, which was responsible for PIWIL1-associated tumor progression." (PMID 33633112, 2021). "We showed that over-expression of RASSF1C in LCSCs enhances the production and size of tumor spheres and implicated PIWIL1 as a potential mediator." (PMID 33227088, 2020). "In the tumor group showing PIWIL1 emerging expression, significant positive associations were observed with lymph node status (p = 0.0065) and macroscopic tumor size (p = 0.21)." (PMID 33008024, 2020). "Subsequently, tumor samples were divided into low or high expression of the PIWIL1 protein according to the ROC curve to associate its expression to survival." (PMID 31443431, 2019). "Decreased or absent PIWIL gene expression associates with more aggressive tumor phenotype and worse survival, indicating that PIWIL1 can serve as potential prognostic biomarkers in patients with RCC." (PMID 31399034, 2019). "We believe that blocking PIWIL1-associated signal transduction pathways can delay tumor growth, proliferation, infiltration, and metastasis." (PMID 28634417, 2017). "PIWIL1 is closely associated with biological behaviors such as proliferation, apoptosis, adhesion, metastasis, and chemotherapy resistance of tumor cells." (PMID 28634417, 2017). "In the other study, the scholars have observed PIWIL1 mRNA expression was significantly associated to the depth of tumor invasion and the stage of tumorigenesis progression of CRC." (PMID 28634417, 2017). "Increased expression of PIWIL1 is associated with enhanced tumor growth increased tumor grades, poor diagnostic outcomes and mortality." (PMID 24932571, 2014). "Their contribution to tumor progression may be explained by the maintenance of the CSC subpopulation since PIWIL1 and PIWIL2 have been associated with expression of CSC markers and increased tumor formation, migration and invasion." (PMID 38303021, 2024). "Importantly, overexpression of the PIWIL1 gene is common to many tumor types, and its aberrant overexpression has been associated with tumorigenesis, tumor development and poor prognosis in different tumors." (PMID 33718392, 2021). "Roles, cellular functions and underlying mechanisms of PIWIL1 in tumor cells." (PMID 33718392, 2021). "The association between PIWIL1 expression and clinicopathological factors of tumor." (PMID 33718392, 2021). "Whether genomic mutations in PIWIL1 gene are associated with induced PIWIL1 expression remains unclear, and the functional consequences of such mutations in tumor cells are not well understood." (PMID 33718392, 2021). "Once we had demonstrated that Piwil1 was associated with the acquisition of stem-like features, we next considered whether this stem-like phenotype was associated with particular tumor biology properties." (PMID 26506848, 2015). "In this study, we investigated the clinical and molecular significance of piR-823 in OC and explored its potential regulatory role in tumor progression through a proposed epigenetic axis involving PIWIL1, DNMT3B, and CDH1." (PMID 41596471, 2026). "Single-cell analysis of the tumor microenvironment revealed predominant PIWIL1 expression in epithelial cells, with significantly higher levels in LOCRC, particularly in CMS1 and CMS3 subtypes." (PMID 40301858, 2025).
tumor (continued). "PIWIL1 overexpression correlates with poor tumor differentiation, infiltration, lymph node invasion, metastasis, and reduced overall and disease-free survival in CRC." (PMID 40301858, 2025). "In a previous study conducted by our research group, we showed that the PIWIL1 protein, which is involved in the biogenesis of piRNAs, becomes reactivated in the tumor tissues of some NSCLC patients." (PMID 40243460, 2025). "Tumor cells increase Piwi-like RNA-Mediated Gene Silencing 1 (PIWIL1) to boost oxygen consumption and energy production through fatty acid metabolism, advancing HCC progression." (PMID 38297372, 2024). "PIWIL1 overexpression accelerates energy production by promoting fatty acid metabolism to meet the needs of rapid tumor growth in HCC cells." (PMID 38031146, 2023). "HCC cells increased intracellular free fatty acid consumption, leading to PIWIL1-mediated promotion of fatty acid metabolism to speed up energy production to meet the needs of rapid tumor growth." (PMID 38031146, 2023). "An important gene that controls the ncRNA-mediated cell proliferation of both embryo and tumor development is the PIWI-like RNA-mediated gene silencing 1 (PIWIL1)." (PMID 36980876, 2023). "PIWIL1 can bind with a new class of low scores of non-coding RNA piRNAs, which regulate tumor proliferation, metastasis, invasion, and prognosis." (PMID 38012622, 2023). "In contrast, downregulated expression of PIWIL1, PIWIL2, and PIWIL4 genes was observed in high-stage RCC tumour samples and was associated with worse overall survival (OS) of patients." (PMID 35204687, 2022). "The overexpression of PIWIL1 exerted an influential role in maintaining stem cell-like characteristics, including enhanced tumor cell viability, migration, invasion, and sphere formation activity." (PMID 36212439, 2022). "Immunohistochemical analysis revealed that PIWIL1 expression correlated with higher tumour grade and clinical staging, distant metastasis, and shorter CSS (cancer-specific survival), as well as high pre-operative CRP levels." (PMID 35204687, 2022). "As an important member of the Argonaute protein family, PIWI-like protein 1 (PIWIL1) plays a key role in tumor cell viability." (PMID 35083142, 2021). "On the contrary, reduced infiltration of M-MDSCs in the liver and tumor tissues were observed in PIWIL1-overexpressing HCC tumors." (PMID 33633112, 2021). "Twelve studies showed significant differences in PIWIL1 mRNA expression between tumor and normal tissues." (PMID 33718392, 2021). "To investigate if the infiltration of PMN-MDSCs in the surrounding hepatic tissues contributes to the tumor-promoting effect of PIWIL1 in HCC, we depleted this population using a specific anti-Ly6G antibody." (PMID 33633112, 2021). "The tumor burden was significantly higher in PIWIL1+ mice than in control mice and significantly lower in PIWIL1– mice." (PMID 35083142, 2021). "Growing evidence showed that PIWIL1 tends to exhibit tumor-promoting roles in sustaining tumor cell proliferation and activating invasion and metastasis." (PMID 33718392, 2021). "MiR-154-5p overexpression targets PIWIL1 to suppress cell metastasis and proliferation, suggesting it plays a tumor-suppressive role." (PMID 34857012, 2021). "PIWIL1 plays a vital role in MM tumor progression and drug resistance by modulating mitophagy and regulating MM stem cells, and PIWIL1 suppression appears to be a promising novel therapeutic strategy for MM." (PMID 35083142, 2021). "For example, myeloid-derived suppressor cells (MDSCs) are drawn to the tumor microenvironment by PIWIL1-overexpressed HCC cells." (PMID 34869376, 2021). "Several strategies have been developed to target PIWIL1 in tumor cells either directly or indirectly." (PMID 33718392, 2021). "PIWIL1 is an important member of the Argonaute protein family that is closely related to the biological behaviors of tumor cell proliferation, apoptosis, adhesion, metastasis, and chemotherapy resistance." (PMID 33854615, 2021).
tumor (continued). "PIWIL1 was reported to participate in tumor progression via piRNA-dependent or -independent mechanisms." (PMID 34922552, 2021). "To further examine if the PIWIL1-induced in vitro proliferation of HCC cells conferred to the in vivo tumor growth in the liver, we established murine models of both xenograft and orthotopic HCC." (PMID 33633112, 2021). "Most studies found that PIWIL1 knockdown suppresses tumor cell and stem cell growth by regulating cell cycle arrest, senescence, or apoptosis." (PMID 35083142, 2021). "PIWIL1 was exclusively observed in the cytoplasm of tumor cells and PIWIL2 was identified in the nucleus." (PMID 33008024, 2020). "PIWIL1-2-3-4 proteins are expressed both in epithelial cancer cells and in different subpopulations of tumor microenvironment in IBCs." (PMID 33008024, 2020). "IHC assay confirmed PIWIL1-2-3-4 proteins localization in breast epithelial cancer cells and several subtypes of stromal and inflammatory/immune cells of the tumor microenvironment." (PMID 33008024, 2020). "The PIWIL1/piRNA-DQ593109 (piR-DQ593109) is known to be a central regulator of blood-tumor barrier (BTB) permeability." (PMID 33109195, 2020). "High PIWIL1 expression in tumor tissue is closely related to the tumor differentiation degree, infiltration depth, lymph vascular invasion, lymph node metastasis, and TNM stage." (PMID 31399034, 2019). "Meanwhile, they further found the hypomenthylation in one tumor sample with higher expressed PIWIL1 and hypermethylation in another tumor sample with lower expressed PIWIL116." (PMID 29168346, 2018). "That is to say, PIWIL1 protein is only present in cytoplasm of the tumor cells in another 97 samples." (PMID 28634417, 2017). "In these 110 cases of CRC tissues, 13 samples were found in PIWIL1 protein common expressed in the cytoplasm and nucleus of the tumor cells." (PMID 28634417, 2017). "The expression of PIWIL1 was closely related to the tumor differentiation degree, infiltration depth, lymphovascular invasion, lymph node metastasis, and TNM stage (P < 0.05)." (PMID 28634417, 2017). "We discovered from the immunohistochemical results that PIWIL1 was mainly located in the cytoplasm of the tumor cells; a small proportion of PIWIL1 was also expressed in the nucleus." (PMID 28634417, 2017). "The expression of PIWIL1 was closely related to the tumor differentiation degree, infiltration depth, lymphovascular invasion, lymph node metastasis, and TNM stage." (PMID 28634417, 2017). "Piwil1 was only detected in the cytoplasm of tumor cells in few cases, while Piwil2 and Piwil4 were detected in most of the cases." (PMID 27329591, 2016). "To better investigate the role which human PIWIL1 protein plays in tumor cells, we performed a bacterial two-hybrid screen using PIWIL1 as the bait and detected STMN1 as a PIWIL1-interacting protein." (PMID 26317901, 2015). "To further investigate the signaling pathway through which PIWIL1 regulates in tumor cells, we performed a bacterial two-hybrid assay using PIWIL1 as the bait and identified STMN1 as a target-protein." (PMID 26317901, 2015). "Conversely, Piwil1 knockdown inhibited cell viability, migration, invasion, sphere-forming activity in vitro and tumor formation in xenograft model in vivo." (PMID 26506848, 2015). "The result that PIWIL1 overexpression promotes the tumor migration was also verified by wound-scratch (healing) assay." (PMID 26317901, 2015). "In tumor tissue, PIWIL1 expression was detected in eleven patients (15.5%), PIWIL2 in 66 (93%), PIWIL3 in five (7%) and PIWIL4 in 60 (84.5%)." (PMID 25742785, 2015). "Overexpression of Piwil1 functioned to maintain stem-like characteristics, including enhancing tumor cell viability, migration, invasion and sphere-forming activity." (PMID 26506848, 2015). "Knockdown of PIWIL1 compromised sphere formation ability in the stem cell population SSClo Aldebr and in vivo tumor growth in a nude mice model." (PMID 25742785, 2015).
tumor (continued). "In situ hybridization on tumor sections revealed that L1, PIWIL1, 2 and MAEL are specifically expressed in epithelial cells (cancerous cells) of EOC." (PMID 24932571, 2014). "One of the tumor suppressors down-regulated by PIWIL1 is IGFBP-5, which we have previously shown to be an interacting partner of RASSF1C." (PMID 25007054, 2014). "PIWIL1 induces sarcomagenesis through down-regulation of tumor suppressors and cyclin-dependent kinase inhibitors via hypermethylation." (PMID 25007054, 2014). "Recent studies show that over-expression of PIWIL1 promotes sarcomagenesis and down-regulates a number of tumor suppressors, including insulin-like growth factor binding protein 5 (IGFBP-5)." (PMID 25007054, 2014). "Moreover, the upregulated PIWIL1 in gastric cancer samples significantly correlated with tumor node metastasis but inversely with the degree of differentiation." (PMID 38031146, 2023). "PIWIL1, which is expressed by tumor cells, could be a viable target for the development of new HCC treatments." (PMID 34869376, 2021). "Overexpression of PIWIL1 could significantly induce tumor growth in HCC xenograft, while PIWIL1 knockdown showed the opposite effect." (PMID 33633112, 2021). "In tumor tissues, PIWIL1 is frequently overexpressed in tumor tissues compared with normal tissues." (PMID 33718392, 2021). "RNA-seq analysis revealed that immune system regulation might be involved, which was echoed by the experimental observation that PIWIL1-overexpressing HCC cells attracted myeloid-derived suppressor cells (MDSCs) into the tumor microenvironment." (PMID 33633112, 2021). "RNA sequencing analysis revealed that PIWIL1-induced FAO might alter the immune cells in the tumor microenvironment of HCC." (PMID 33633112, 2021). "A deeper understanding of the crosstalk between PIWIL1 and other signaling pathways would be important to design effective therapeutic strategies that could sensitize PIWIL1-expressing tumor cells to chemotherapeutic agents or targeted therapies." (PMID 33718392, 2021). "These factors may, therefore, lead to a tumor inhibition at the same degree in wild type HCC compared with PIWIL1-overexpressing HCC." (PMID 33633112, 2021). "Taken together, these observations confirmed that PIWIL1 could facilitate in vitro cell proliferation and in vivo tumor growth in HCC." (PMID 33633112, 2021). "We identified immunostaining of tumor cells with anti-PIWIL1 antibodies in 34,6% of IBCs (n = 52) and anti-PIWIL3 antibodies in 8% of IBCs (n = 12) and absence or slight staining with anti-PIWIL2 antibody in 48,3% of IBCs (n = 67) and anti-PIWIL4 antibody in 48,6% of IBCs (n = 73)." (PMID 33008024, 2020). "Indeed, PIWIL1 expression in CRC has recently been correlated with tumor differentiation, infiltration, lymph node invasion, and metastasis and has been tightly associated with BRAF gene mutation (V600E) and poor prognosis." (PMID 31694219, 2019). "PIWIL1 mainly localizes in the cytoplasm of CRC tumor cells." (PMID 31399034, 2019). "In fact, PIWIL1 expression was also detected in the cytoplasm of some stroma cells, although all the cases with positive stained stroma cells showed stronger positiveness in tumor cells than in the stroma." (PMID 31443431, 2019). "Moreover, PIWIL1 up-regulation in EC causes the loss of phosphatase and tensin homolog deleted on chromosome ten (PTEN) expression, which serves as an essential tumor suppressor role in EC through DNMT1-mediated PTEN hypermethylation." (PMID 31399034, 2019). "Similarly, we observed a striking pattern of PIWIL1 overexpression in our tumor tissues (P < 0.001) by Real‐Time PCR (RT‐PCR)." (PMID 29168346, 2018). "We found that PIWIL1 was mainly located in the cytoplasm of the CRC tumor cells." (PMID 28634417, 2017). "This bias might partly be explained by the preferential usage of either Piwil1 or Piwil2 in these tumor types as indicated by qPCR." (PMID 27183847, 2016).
tumor (continued). "Thus PIWIL1 inhibits microtubule polymerization and enhances tumor cell proliferation, migration and invasion." (PMID 26317901, 2015). "We next detected whether PIWIL1 can regulate tumor cell migration and invasion by performing Transwell assays." (PMID 26317901, 2015). "Stem cell protein Piwil1 functions as an oncogene in various tumor types." (PMID 26506848, 2015). "Since PIWIL1 was highly expressed during early lung development and PIWIL1 expression in tumor tissue was a marker of poor prognosis, we postulated that its expression could be associated with stem-cell characteristics." (PMID 25742785, 2015). "Tumor cells-expressed PIWIL1 may be a potential target for the development of novel HCC treatment." (PMID 33633112, 2021). "However, evidence also supports a tumor suppressor role for PIWIL1 in some cell types." (PMID 33718392, 2021). "However, the molecular mechanism of PIWIL1 in tumor cells remains to be intangible." (PMID 26317901, 2015). "We surmise whether PIWIL1 promotes tumor cell proliferation and invasion via STMN1." (PMID 26317901, 2015). "In another study, the expression of PIWIL1 contributed to a more sophisticated classification of RCC patients, particularly those exhibiting elevated Fuhrman grade, advanced tumor stage, and distant metastasis." (PMID 40737301, 2025). "PIWIL1 forms a complex with UPF1, UPF2, and SMG1, which creates NMD machinery that degrades mRNAs and lncRNAs, supposedly resulting in tumor growth." (PMID 39596284, 2024). "The comparison of the mRNA expression levels of 32 genes of the 21 CTAs between relatively healthy and tumor ovarian tissue showed up-regulation in the expression level of the AKAP3, MAGEA4, PIWIL1, and PRAME genes in tumor samples." (PMID 37835834, 2023). "Overexpression of PIWIL1 inhibits the apoptosis of CRC cells, promotes angiogenesis, and increases tumor volume and weight in nude mice, thus promoting the malignant progression of CRC." (PMID 38031146, 2023). "The high PIWIL1 expression in GBM correlates with larger tumor diameter and higher tumor grade, promoting the malignant proliferation of glioma stem cells (GSCs)." (PMID 38031146, 2023). "The expression of PIWIL1-4 genes was analysed in paired ccRCC-normal tissue samples, and higher expression of PIWIL4 in tumour tissue was observed." (PMID 35204687, 2022). "It has been found that PIWI proteins in human and mice, such as PIWIL1, PIWIL2, PIWIL2 proteins, and HIWI are expressed in various types of tumor cells." (PMID 33673453, 2021). "PIWIL1, PIWIL2 and PIWIL4 were also localized within the nucleus and the cytoplasm of several subtypes of cells belonging to the tumor microenvironment such as immune cells, endothelial cells and fibroblasts." (PMID 33008024, 2020). "PIWIL1, PIWIL2, PIWIL3 and PIWIL4 were all deregulated with a dissociated profile: PIWIL1 and PIWIL3 had an abnormal emergent expression and the remaining PIWIL2 and PIWIL4 were variably downregulated in tumor tissues at RNA and protein levels." (PMID 33008024, 2020). "PIWIL1 and PIWIL2 showed very scarce expression in all pancreatic cell lines, not only in the tumor-derived but also in the non-tumor cell lines." (PMID 32357464, 2020). "PIWIL1 and PIWIL2 mRNAs expression resulted altered in tumor tissues, confirming previous observations in HCC." (PMID 27429044, 2016). "Comparison with normal breast tissues revealed that two genes (PIWIL1 and PIWIL3) were up-regulated and the remaining two (PIWIL2 and PIWIL4) were down-regulated in tumor tissues." (PMID 27177224, 2016). "The PIWIL1/STMN1/tubulin complex suppresses MT polymerization and thus promotes tumor cell migration and proliferation." (PMID 26317901, 2015). "Our work shows that PIWIL1 and MAEL expression is significantly increased in malignant EOC (n = 25) compared to benign tumor tissues (n = 19) and normal ovarian tissue (n = 8)." (PMID 24932571, 2014).